NAMPT (nicotinamide phosphoribosyltransferase)
Diseases named in the same sentence as NAMPT in open-access papers (continued):
Sharing a sentence is not in itself a finding about the gene and the disease.
Stroke (5 papers, 2020 to 2025). Sudden impairment of blood flow to a part of the brain due to occlusion or rupture of an artery to the brain. "Moreover, metformin is reported to lessen the risk of stroke by enhancing autophagy, while nicotinamide phosphoribosyl transferase (NAMPT) promotes cell survival by regulating autophagy after cerebral ischemia." (PMID 33688357, 2020). "The key genes encompass critical pathways such as autophagy (e.g. NFE2L2, DDIT3, NAMPT), apoptosis (e.g. CFLAR, FADD) and NF-κB signaling (e.g. RELA, TNFSF10), suggesting a multifactorial involvement of these pathways in stroke pathophysiology." (PMID 40969765, 2025). "Although neurons activate compensatory NAD+ salvage through nicotinamide phosphoribosyltransferase (NAMPT), this pathway fails to offset PARP-1-driven NAD+ catabolism during stroke, resulting in sustained sirtuin suppression and disrupted mitochondrial dynamics." (PMID 41184254, 2025).
atopic dermatitis (4 papers, 2020 to 2025). "This narrative review summarizes the current knowledge on how elafin, chemerin, and nicotinamide phosphoribosyltransferase (visfatin/NAMPT) contribute to the pathophysiology of skin inflammation in atopic dermatitis." (PMID 40969761, 2025).
breast tumor (4 papers, 2012 to 2021). "We observed in metabolic pathways by quantitative PCR analyses that NAMPT is overexpressed in breast tumor tissue and FGFR4 deficiency downregulates the expression." (PMID 24279986, 2013). "NAMPT as a downstream target of FGFR4 deficiency and FGF21 elevation is highly expressed in breast tumor foci but attenuated by the FGFR4 deficiency." (PMID 24279986, 2013). "Treatment with a chemical inhibitor of NAMPT involved in the pathways inhibited the growth and survival of breast tumor cells and tumor-initiating cell-containing spheres." (PMID 24279986, 2013). "Furthermore, our study provided potential new targets, such as FGF21, adiponectin, NAMPT and Acly, for suppressing breast tumor malignancy concurrently with inhibition of FGFR." (PMID 24279986, 2013). "In addition to increasing PHGDH, an increase of nicotinamide phosphoribosyltransferase (NAMPT), a rate-limiting enzyme of NAD+ salvage pathway, was also shown in ER-negative breast cancer lines and patient-derived breast tumors." (PMID 30857125, 2019).
Cerebral ischemia (4 papers, 2013 to 2026). Restriction of arterial blood supply to the brain associated with insufficient oxygenation to support the metabolic requirements of the tissue. "Autophagic activation is involved in the neuroprotective effects of nicotinamide phosphoribosyltransferase and hamartin against cerebral ischemia." (PMID 32549974, 2020). "After cerebral ischemia, total NAMPT protein level in the ischemic core increased by 39%, 70% and 106%, whereas NAMPT mRNA level in the ischemic core decreased by 35%, 47% and 50% at 6, 12 and 24 h after reperfusion, respectively." (PMID 24392007, 2013). "Our finding established the functional role of extracellular NAMPT protein in cerebral ischemia." (PMID 24392007, 2013). "Thus, neutralizing the non-enzymatic activity of NAMPT can be a novel therapeutic strategy for the treatment of cerebral ischemia, especially for patients with high eNAMPT level in serum." (PMID 24392007, 2013). "Thus, eNAMPT is an injurious and inflammatory factor in cerebral ischemia and aggravates ischemic neuronal injury by triggering TNF-α release from glia cells, via a mechanism not related to NAMPT enzymatic activity." (PMID 24392007, 2013).
chondrosarcoma (4 papers, 2019 to 2022). A malignant cartilaginous matrix-producing mesenchymal neoplasm arising from the bone and soft tissue. "Our research group published that the reported synthetic lethal interaction between IDH mutations and Bcl-2, NAMPT, and glutaminase inhibition was absent in chondrosarcoma." (PMID 31810230, 2019). "These drugs either have a known synergistic effect with HDAC inhibitors (e.g., chemotherapy and proteasome inhibitors) or were previously successful as single agent in chondrosarcoma cell lines (e.g., PARP and NAMPT inhibitors)." (PMID 33266275, 2020).
coronary artery disease (4 papers, 2013 to 2025). "We investigated association of circulating NAMPT levels and the rs9770242 NAMPT gene polymorphism with coronary artery disease (CAD)." (PMID 23968400, 2013).
glaucoma (4 papers, 2022 to 2026). Increased pressure in the eyeball due to obstruction of the outflow of aqueous humor. "Next, the expression analysis of the three diagnostic biomarkers in glaucoma and control samples confirmed that NAMPT and ADH1C were up-regulated in glaucoma samples, and ENO2 was down-regulated." (PMID 35366826, 2022). "Our research shows that ENO2, NAMPT, and ADH1C as diagnostic markers have been proved to be effective in the diagnosis of glaucoma, and ENO2 is a potential therapeutic target." (PMID 35366826, 2022). "The loss of neuronal NAMPT will lead to motor neuron degeneration and functional defects in mice, and NAMPT has an important impact on human neurological diseases, this is consistent with the high expression of NAMPT in glaucoma samples." (PMID 35366826, 2022). "In conclusion, our research shows that ENO2, NAMPT, and ADH1C can be used as diagnostic markers for glaucoma, and ENO2 can be used as a therapeutic target." (PMID 35366826, 2022). "Nicotinamide supplementation has demonstrated neuroprotective potential in glaucoma by raising retinal and optic nerve nicotinamide adenine dinucleotide (NAD) via the salvage pathway, dependent on nicotinamide phosphoribosyltransferase (NAMPT)." (PMID 41603715, 2026). "NAMPT and ADH1C were up-regulated in glaucoma samples, contrary ENO2 was down-regulated in glaucoma samples." (PMID 35366826, 2022). "The expression of 3 biomarkers in the GSE9944 dataset suggested that NAMPT and ADH1C were up-regulated and ENO2 down-regulated in glaucoma samples." (PMID 35366826, 2022).
head and neck cancer (4 papers, 2019 to 2025). A primary or metastatic malignant neoplasm affecting the head and neck. "The combination of radiotherapy and GMX1777 that abolishes NAMPT activity has been in vivo tested in head and neck cancer." (PMID 35565188, 2022). "Notably, NAMPT is up-regulated in TANs from human skin cancer as well as head and neck cancer, and NAMPT expression positively correlates with the tumor stage." (PMID 34885082, 2021).
metastatic melanoma (4 papers, 2011 to 2022). A melanoma that has spread from its primary site to another anatomic site. "Using metastatic melanoma (MM) as disease model, we and others previously demonstrated that NAMPT is over-expressed during BRAFi resistance and patient relapse/progression, becoming a driver of targeted-therapy resistance." (PMID 35272691, 2022). "Nicotinamide phosphoribosyltransferase (NAMPT), the rate-limiting enzyme in nicotinamide adenine dinucleotide (NAD) biosynthesis, is up-regulated in several cancers, including metastatic melanoma (MM)." (PMID 35272691, 2022).
myeloid leukemia (4 papers, 2017 to 2023). A clonal proliferation of myeloid cells and their precursors in the bone marrow, peripheral blood, and spleen. "To verify this hypothesis, we evaluated the intracellular NADP(H) content in myeloid leukemia cells upon treatment with NAMPT inhibitors." (PMID 36838885, 2023).
non-alcoholic fatty liver disease (4 papers, 2016 to 2024). "The distribution of NAMPT rs2058539 genotypes and alleles differed significantly between the cases with nonalcoholic fatty liver disease and controls." (PMID 39045924, 2024). "Our findings indicated for the first time that the NAMPT rs2058539 "CC" genotype is a marker of increased nonalcoholic fatty liver disease susceptibility; however, it needs to be supported by further investigations in other populations." (PMID 39045924, 2024). "Disturbances in NAMPT and NAMPT-mediated NAD+ biosynthesis have been reported to contribute to the development of non-alcoholic fatty liver disease (NAFLD) and NAMPT is implicated in the regulation of hepatic lipid metabolism." (PMID 30794635, 2019).
osteoporosis (4 papers, 2017 to 2025). A condition of reduced bone mass, with decreased cortical thickness and a decrease in the number and size of the trabeculae of cancellous bone (but normal chemical composition), resulting in increased fracture incidence. "It is noteworthy that a gene (NAMPT) was found to be shared by multisets, implicating a significant role for NAMPT in both osteoporosis and T2DM." (PMID 35993048, 2022). "NAMPT may be a potential therapeutic target of aging-related osteoporosis." (PMID 28546856, 2017).
acute respiratory distress syndrome (3 papers, 2012 to 2017). Progressive and life-threatening pulmonary distress in the absence of an underlying pulmonary condition, usually following major trauma or surgery. "In a sensitivity analysis limiting ALI cases to those who qualified for the Acute Respiratory Distress Syndrome (ARDS), rs61330082 in NAMPT was nominally associated with risk for ARDS." (PMID 23251429, 2012).
amyotrophic lateral sclerosis (3 papers, 2020). Amyotrophic lateral sclerosis (ALS) is a neurodegenerative disease characterized by progressive muscular paralysis reflecting degeneration of motor neurons in the primary motor cortex, corticospinal tracts, brainstem and spinal cord. "A study indicated that NAMPT enzymatic activity enhancer P7C3 could have a neuroprotective effect in a mouse model of amyotrophic lateral sclerosis (ALS), and the levels of iNAMPT in ALS patients were lower than those of age-matched controls." (PMID 32411700, 2020).
astrocytoma (3 papers, 2014 to 2021). "NAMPT (PBEF1) is shown to be up regulated in malignant astrocytoma and also in serum samples of the patients." (PMID 24475040, 2014).
brain tumor (3 papers, 2017 to 2025). "To confirm the clinical significance of NAMPT expression in brain tumors, we analyzed public available ectoderm-derived tumor datasets for NAMPT levels." (PMID 29245920, 2017). "Furthermore, NAMPT expression was strongly correlated with tumor grade in two independent datasets, indicating that NAMPT is highly overexpressed in human brain tumors and correlates with tumor stage." (PMID 29245920, 2017).
cardiac hypertrophy (3 papers, 2021 to 2024). "Therefore, the RASD1/NAMPT axis emerges as a crucial cellular signalling pathway implicated in the pathogenesis of cardiac hypertrophy." (PMID 39535387, 2024). "Therefore, it demonstrates that oxidative stress, energy synthesis, and disrupted autophagy balance in cardiomyocytes resulting from downregulation of the RASD1/NAMPT axis may underlie the increased cardiac hypertrophy and cardiovascular risk observed in female HCM patients." (PMID 39535387, 2024). "Interestingly, NAMPT heterozygous knockdown prevented cardiac hypertrophy, but genetically modified mice with heart-specific NAMPT overexpression spontaneously developed cardiac hypertrophy." (PMID 39513038, 2024). "Additionally, more pronounced cardiac hypertrophy was observed in SHR females, characterized by reduced left ventricular inner diameters, suggesting that RASD1/NAMPT axis is prabably a key mechanism." (PMID 39535387, 2024).
cardiomyopathy (3 papers, 2021 to 2025). A disease of the heart muscle or myocardium proper. "Interestingly, a study reported that metabolism of NAD+ is altered in Lmna cardiomyopathy: the Nampt mRNA expression, NAMPT protein expression and NAD+ levels were all reduced in the hearts of mice with cardiomyopathy caused by a Lmna mutation." (PMID 36099415, 2022). "Several of the proteins impacted by myectomy (POSTN, MMP12, CDON, NAMPT, HAMP, LTA4H) were previously reported to be altered in cardiovascular disease, cardiomyopathy, or vascular disease with effects mediated through inflammatory mechanisms." (PMID 33804404, 2021). "In summary, we found that administration of the small-molecule compound JQ-1 improved cardiac remodeling after MI by inhibiting ferroptosis through the NAMPT/SIRT1 pathway, indicating a novel potential strategy for the intervention of ferroptosis-related cardiomyopathy." (PMID 40695797, 2025).
Crohn disease (3 papers, 2008 to 2024). A gastrointestinal disorder characterized by chronic inflammation involving all layers of the intestinal wall, noncaseating granulomas affecting the intestinal wall and regional lymph nodes, and transmural fibrosis. "Moreover, it was suggested that NAMPT has potential implications in the pathogenesis of acute lung injury, Crohn's disease (CD), ulcerative colitis (UC), and RA." (PMID 18493620, 2008).
diabetic nephropathy (3 papers, 2022 to 2024). "FK866 previously showed anti-fibrosis and antioxidant effects through maintenance of NAD+ homeostasis during diabetic nephropathy 56, while NAMPT inhibitors were developed for treating cancer, their anti-cancer effects are dose-dependent." (PMID 38773984, 2024). "In short, the results of this study provided the first evidence that NMN accumulation, possibly induced by up-regulation of NAMPT and down-regulation of NMNAT1 in diabetic nephropathy, plays a pathogenic role in DN with regulatory effects on NF-κB P65 and Sirt1 signaling pathways." (PMID 35408818, 2022). "However, surprisingly, opposing studies have revealed that glomerular cells (mesangial cells and podocytes) as well as PTECs increase NAMPT expression in diabetic nephropathy rat models, Otsuka Long-Evans Tokushima fatty (OLETF) rats and STZ-treated rats." (PMID 36611814, 2022).
dilated cardiomyopathy (3 papers, 2015 to 2020). Cardiomyopathy which is characterized by dilation and contractile dysfunction of the left and right ventricles. "This study aimed to determine if the single nucleotide polymorphisms (SNPs) of the NAMPT gene may affect the susceptibility and prognosis for patients with dilated cardiomyopathy (DCM) and to describe the association of serum NAMPT levels with clinical features of DCM." (PMID 26389889, 2015).
esophageal squamous cell carcinoma (3 papers, 2015 to 2025). Esophageal squamous cell carcinoma (ESCC) is a type of esophageal carcinoma (EC) that can affect any part of the esophagus, but is usually located in the upper or middle third. "The present study examines whether genetic polymorphisms of NAMPT are related to the risk of developing esophageal squamous cell carcinoma (ESCC)." (PMID 25896907, 2015).
fibrosarcoma (3 papers, 2016 to 2021). A malignant mesenchymal fibroblastic neoplasm affecting the soft tissue and bone. "Notably, a dependency on QPRT activity was recently observed in human fibrosarcoma cells with acquired resistant to NAMPT inhibition that still presented a point mutation in the NAMPT enzyme." (PMID 29541451, 2018). "For example, on fibrosarcoma cells NAMPT overexpression has been shown to protect cells against FK866 treatment." (PMID 27462772, 2016).
Graves disease (3 papers, 2016 to 2018). Graves' disease is an autoimmune disorder that leads to overactivity of the thyroid gland (hyperthyroidism).It is caused by an abnormal immune system response that causes the thyroid gland to produce too much thyroid hormones. "Simple linear regression analysis revealed that NAMPT/visfatin serum concentration was significantly associated with Graves’ disease (β = 1.5723; p = 0.021)." (PMID 26767650, 2016). "In the stepwise multiple regression analysis, we confirmed the association between higher serum NAMPT/visfatin level and Graves’ disease (coefficient = 1.5723; p = 0.0212), whereas age, BMI, FT3, HOMA-IR, and Graves’ orbitopathy (yes/no) did not contribute significantly." (PMID 26767650, 2016). "At the same time, we have observed increased NAMPT/visfatin/PBEF serum concentration in patients with Graves' disease with and without orbitopathy." (PMID 29546048, 2018). "We have also found NAMPT overexpression in hyperfunctioning thyroid nodules in toxic nodular goiters as compared to Graves' disease without orbitopathy and to healthy controls." (PMID 29546048, 2018). "To investigate the role of NAMPT/visfatin in euthyroid patients with Graves’ disease without (GD) and with Graves’ ophthalmopathy (GO), we analyzed NAMPT leukocyte expression and its serum concentration." (PMID 26767650, 2016).
head and neck squamous cell carcinoma (3 papers, 2021 to 2023). A squamous cell carcinoma that arises from any of the following anatomic sites: lip and oral cavity, nasal cavity, paranasal sinuses, pharynx, larynx, and salivary glands. "NAMPT inhibitor was proved to effectively repress cell growth in head and neck squamous cell carcinoma." (PMID 37065499, 2023). "We found high levels of NAMPT expression in the tumorspheres generated from our head and neck squamous cell carcinoma (HNSCC) cell lines." (PMID 36078035, 2022).
inflammatory skin disease (3 papers, 2021 to 2025). Inflammatory skin disorders covers a broad category that includes many conditions ranging in severity, from mild itching to grave medical health complications These disorders are common in people of all ages and races. "Clinical data also support the role of these signaling pathways in PS, pointing to NAMPT and PARP1 as potential new therapeutic targets in treating inflammatory skin disorders." (PMID 37175698, 2023).
injury (3 papers, 2015 to 2020). Damage inflicted on the body as the direct or indirect result of an external force, with or without disruption of structural continuity. "In this study, we further determined the role of NAMPT enzymatic activity in the pathogenesis of I/R-induced acute lung injury using an inhibitor of NAMPT enzymatic function, FK-866." (PMID 28438162, 2017). "The mechanisms by which NAMPT exerts these detrimental effects in VILI are unclear and understanding of the downstream pathways affected by NAMPT will be important for understanding the pathogenesis of acute lung injury." (PMID 25875775, 2015). "Nicotinamide (vitamin B3) directly inhibits downstream pathways activated by Nicotinamide phosphoribosyltransferase and is protective in other models of acute lung injury." (PMID 25875775, 2015). "However, it remains unclear whether NAMPT inhibition has an impact on ischemia-reperfusion (I/R)-induced acute lung injury." (PMID 28438162, 2017).
liver disease (3 papers, 2017 to 2020). "Serum NAMPT levels are altered in various diseases, for example in liver diseases." (PMID 28974242, 2017). "Other studies regarding upstream regulators of SIRT1, such as IRF9/PPAR-α, NAMPT/NMNAT, HuR, AMPK, PARP1, CK2 and cathepsins have pointed to these proteins as possible therapeutic targets for the treatment of various inflammatory pathologies, including liver diseases." (PMID 32485811, 2020).
lymph node metastasis (3 papers, 2019 to 2021). "Moreover, a univariate analysis of clinical information showed that the NAMPT expression was significantly correlated with age, gender, tumor grade, lymph node metastasis, and tumor diameter." (PMID 33540574, 2021). "Our present study found that NAPRT and NAMPT were both highly expressed in CRC tissues, and correlate with vascular invasion, higher T-stage, lymph node metastasis and advanced TNM stage." (PMID 31448236, 2019).
mantle cell lymphoma (3 papers, 2019 to 2022). Mantle cell lymphoma is a rare form of malignant non-Hodgkin lymphoma affecting B lymphocytes in the lymph nodes in a region called the ``mantle zone''. "KPT–9274 is recognized as a dual inhibitor of PAK4 and NAMPT, which is capable of effectively inhibiting the growth of mantle cell lymphoma, follicular lymphoma, and diffuse large B-cell lymphoma." (PMID 35800076, 2022).